CD1D (CD1d molecule)
Diseases named in the same sentence as CD1D in open-access papers (continued):
Sharing a sentence is not in itself a finding about the gene and the disease.
infection (96 papers, 2008 to 2026). The state of being infected such as from the introduction of a foreign agent such as serum, vaccine, antigenic substance or organism. "JNK−/− mice are highly resistant to A. phagocytophilum infection, and this has been linked to the repressive role of JNK on CD1d-restricted natural killer T cells production of IFNγ, a cytokine that is critical for clearing the infection in mice." (PMID 38415594, 2024). "Mrp1 deficiencies in macrophages:-Reduce CD1d clustering on the surface;-Induce lower activation of iNKT cells;-Increase mortality associated with the infection." (PMID 35163561, 2022). "A significant decrease in the number of neutrophils, eosinophils, and CD103+DCs infiltrating to the lungs, as well as an increased production of IFN-γ, were observed upon hRSV-infection in CD1d-deficient BALB/c mice, as compared to wild-type control mice." (PMID 32463330, 2020). "Conversely, CD1d-deficient mice that lack iNKT cells exhibit delayed fungal clearance following infection by A. fumigatus." (PMID 29928278, 2018). "In mice, iNKT cells appear to strongly influence HSV-2 replication as CD1d-deficient animals are 10-fold more susceptible to severe infection compared to wild-type controls." (PMID 26161082, 2015). "We observed that the virus loads were significantly higher in the spleens and spinal cords of CD1d-deficient mice compared with WT mice on days 2 and 4 post-infection." (PMID 25615690, 2015). "Consistent with the results in C57BL6 background, we found that CD1d-/- mice were less susceptible to LVS infection in the BALB/c background as well." (PMID 26068662, 2015). "This may explain the relatively low CD1d downregulation at 16 hours post infection by UL56-deficient viruses, compared to that in cells ectopically expressing US3." (PMID 40047437, 2025). "Thus, impaired trafficking of cytotoxic cells is coupled with enhanced trafficking of infected cells and infection targets to the dLNs in the context of CD1d deficiency." (PMID 39088280, 2024). "In addition, we anticipate that CD1d-associated lipidomes will show temporal changes in response to environmental exposures (e.g. diet, infection) and possibly other processes such as aging." (PMID 35874748, 2022). "In addition, an in vivo study of S. pneumoniae infection showed that Mrp1 deficiencies in macrophages reduced CD1d clustering at the cell surface, inducing lower activation of iNKT cells and resulting in increased mortality associated with the infection." (PMID 35163561, 2022). "Furthermore, CD1d-deficient mice poorly control infections with Aspergillus fumigatus reflecting the need for NKT cells in the control of fungal infections." (PMID 34595131, 2021). "Interestingly, the acute infection of mice with LCMV caused a reduction in CD1d cell surface expression on dendritic cells and macrophages." (PMID 34579186, 2021). "In addition, the markedly impaired IL-4 production in CD1d KO mice resulted in an impaired MNV-S7-specific secretory IgA production after MNV-S7 infection which is associated with mucosal immunity." (PMID 31909227, 2020). "Importantly, the expression of CD1d is decreased in alveolar macrophages from hRSV– and hMPV– infected mice, and it has been previously reported that alveolar macrophages exert a protecting role in hRSV whereas being pathogenic during hMPV infection." (PMID 32463330, 2020). "Using a US3-deficient virus, we demonstrated that US3 is required for optimal CD1d downregulation during infection." (PMID 40047437, 2025). "The cells were examined at different time points post infection and subjected to flow cytometry to examine the CD1d downregulation." (PMID 40047437, 2025). "At 30 hours post infection, slight downregulation of CD1d can be detected in mutant virus-infected cells, while there is significantly more downregulation in WT virus-infected cells." (PMID 40047437, 2025).
infection (continued). "The absence of invariant NKT cells caused a slight but significant delay in the resolution of infection and a significant increase in bacterial burden during the infection compared to WT controls or CD1d−/− mice." (PMID 41305402, 2025). "To further characterize the subsets of NKT cells in the LNs following infection in WT and CD1d-KO mice, we sorted NK1.1+CD3+ cells for TCR sequencing." (PMID 39088280, 2024). "Epidermal keratinocytes express substantial levels of CD1d and are a primary site of infection by the herpesvirus HSV-1." (PMID 39355244, 2024). "By using mouse models of CD1d deficiency, we showed that IFN-γ derived specifically from CD1ddep NKT cells during primary DENV infection was instrumental in defining infection outcomes during a secondary DENV infection." (PMID 39088280, 2024). "At 48 hours after infection, significant reductions in the mRNA expression levels of Cxcl9 and Cxcl10 were detected in the FP skin of CD1d-KO mice compared with WT mice." (PMID 39088280, 2024). "For this, we purified serum IgGs from naive WT, DENV2-immune WT, and DENV2-immune CD1d-KO mice 28 days after infection prior to adoptive antibody transfer and challenge of recipients." (PMID 39088280, 2024). "We observed significantly higher numbers of newly recruited, CFSE– NKT-like cells in the skin of WT mice compared with CD1d-KO mice on day 3 after infection." (PMID 39088280, 2024). "At day 3 after infection, we observed increased infection in the LNs of mice that had been transferred CD1d-KO NKT cells compared with WT NKT cells." (PMID 39088280, 2024). "In CD1d-KO mice, Th1-polarized immunity and infection resolution were impaired, which was dependent on intrinsic NKT cell production of IFN-γ, since it was restored by adoptive transfer of WT but not IFN-γ–KO NKT cells." (PMID 39088280, 2024). "Next, to examine how CD1ddep NKT cells affect virus clearance, we measured the infection burden at the site of infection, the FP skin, and in the dLNs of WT and CD1d-KO mice on days 3 and 5 after DENV2 infection." (PMID 39088280, 2024). "In the homologous challenge model, IgGs from DENV2-immune WT mice provided protection against DENV2 infection, resulting in reduced viral titers compared with the IgGs from naive or CD1d-KO infection groups." (PMID 39088280, 2024). "To determine if the loss of Cd1d-restricted NKT cells would impact IFNγ production, we tested serum samples from WT and CD1d−/− mice 4 h after infection and analyzed samples for IFNγ via luminex." (PMID 39445806, 2024). "For this, we infected WT and CD1d-KO mice with DENV2 and determined DENV2-specific serum IgG2a (Th1-associated) and IgG1 (Th2-associated) antibody titers at 5 weeks after infection." (PMID 39088280, 2024). "The differences in viral genome copies were not significantly different in the FP and dLNs at day 3 after infection between WT and CD1d-KO mice." (PMID 39088280, 2024). "Taken together, these results suggest that CD1d plays an important role in PAMs infection with ASFV, especially in the early stages of virus entry." (PMID 37254454, 2023). "In this work, we show that the CD1d-iNKT cell-dependent effect of 7DW8-544,50 prevents infection by SARS-CoV-2, respiratory syncytial virus (RSV), and influenza virus in animal models." (PMID 37402814, 2023). "Despite the low expression of CD1d in DCs, we detected a substantial and reproducible decrease of CD1d expression in infected DCs 24 hours post infection." (PMID 36961850, 2023). "To assess the direct role of iNKT cells in NrHV infection we analyzed the course of infection and extend of liver injury in NKT cell deficient CD1d-/- mice as compared to C57BL/6 WT control mice." (PMID 36159876, 2022). "We observed that infection of Balb/c mice with P. yoelii I 7XL was lethal, and a rapid increase in dynamics of IL-10 producing B220+CD5+CD1d+ regulatory B cells over the course of infection was observed." (PMID 35625397, 2022).
infection (continued). "The contribution of NKT cells to the increased IFN-γ production during the first 24h of infection was confirmed by a drastic drop in IFN-γ serum levels as a result of anti-CD1d treatment." (PMID 34292975, 2021). "T. evansi infections result in a very significant decline in cell numbers of B220+CD1d+ MZBs starting on day 14 post infection, and B220+CD1d- FoBs at the late stage." (PMID 34762705, 2021). "The CD1d-dependent activation of NKT cells plays an important role in resisting EMCV infection because Cd1d−/− mice demonstrated more brutal paralysis due to an acute cytopathic effect of EMCV on neuronal cells." (PMID 34579186, 2021). "Bioluminescent imaging of the MIL-RPpyRE9/DsRed infection dynamics revealed significantly increased liver burdens in anti-CD1d as compared to isotype treated BALB/c and C57Bl/6 mice." (PMID 34292975, 2021). "The mechanism responsible for the insufficient MNV-S7 clearance in CD1d KO mice was attributed to reduced IFN-γ production early during MNV-S7 infection." (PMID 31909227, 2020). "Correspondingly, CD1d KO mice had an almost 1000-fold higher MNV-S7 burden in the intestine after infection in comparison to WT mice." (PMID 31909227, 2020). "Considering all this and in relation with the down-modulation of CD1d detected previously, both hRSV- and hMPV-infections seem to impair the production of IL-2 by iNKT cells in response to α-GalCer-loaded APC." (PMID 32463330, 2020). "Intravital microscopy was used to quantify joint invasion 24 h after i.v. infection of Cd1d-/- BALB/c mice with GFP-producing strains provided a direct means to interrogate a role for OspC in joint tissue invasion." (PMID 32413091, 2020). "They represent a first-line of host defense against pathogen infection similar to B-1 cells and infection-induced antibody production by MZB cells is influenced by CD1d." (PMID 32635160, 2020). "This first piece of data suggests that iNKT cell play a role during the pathogenesis of both viruses, as their infection modulates the expression of the CD1d molecule during the disease." (PMID 32463330, 2020). "CD1d-/- mice had increased bacterial burden in the liver and kidney compared to B6 mice at 4 days post infection (dpi), though both groups had equivalent burdens by 8 dpi, which suggested that NKT cells were necessary for early control of bacterial growth." (PMID 33312179, 2020). "Four weeks after infection significantly lower percentage of CD11c+, CD11c+CD11b+, and CD11c+CD1d+ dendritic cells was detected in the livers of Lgals3−/− mice compared with WT mice." (PMID 31231399, 2019). "This indicates that the APCs of patients who are able to control infection possess other characteristics that modulate specific iNKT activity despite increased CD1d expression on their APCs." (PMID 31253189, 2019). "Both PLE and BAL cells expressed CD1d molecule and a significant up-regulation of its expression occurred upon infection of these cells with BCG." (PMID 30596774, 2018). "During infection triggering of a combination of PRRs stimulates IL-12 release from DCs and increases the presentation of antigenic self-lipids by CD1d." (PMID 29616036, 2018). "Our findings are in line with the notion that NKT cell activation after infection is the result of a combination of both CD1d and cytokine signaling, with CD1d helping to position the cells and cytokines inducing the effector functions of NKT cells." (PMID 29249358, 2018). "When analyzed 4 days after infection, viral titers showed that clearance of virus in response to α-GC was dependent on the CD1d molecule." (PMID 28570692, 2017). "Nevertheless the frequency of CD1d-tetramer+ cells in the CD11c+ T cell fraction decreased in the GT after infection." (PMID 27119555, 2016).
infection (continued). "In the P. yoelii model, primary infection with a late-stage GAP increased the number of IFN-γ secreting CD1d-restricted NKT cells in the liver thus implicating IFN-γ as a crucial innate factor in controlling secondary infection with WT XNL parasites." (PMID 26074888, 2015). "At the lower dose of EV71M infection (2×104 PFU), only 10% (1/10) of WT mice exhibited ruffled hair and hunchback, while 40% (6/15) CD1d-deficient mice had symptoms of limb weakness or paresis and higher average clinical scores." (PMID 25615690, 2015). "We also observed that 75% of CD1d-knockout mice upon oral infection of EV71M developed disease and had significantly higher clinical score than WT mice, as all the wild type mice survived without any palpable symptoms after the infection." (PMID 25615690, 2015). "Our studies revealed that acute LVS infection of CD1d-/- mice resulted in increased lymphocytic infiltration in the lung interstitium when compared to B6 mice." (PMID 26068662, 2015). "The Gram-positive pathogenic bacterium Streptococcus pneumoniae is known to contain an α-glycosyl diacyl glycerol glycolipid antigen that is presented by CD1d to iNKT cells, and efficient clearance of this infection in mice requires iNKT cells." (PMID 24412610, 2014). "After 24 hours, H37Rv infection led to a modest increase in CD1d surface expression on macrophages (1.5±0.1 fold change) (mean ± SEM, n = 13 experiments, p<0.0001)." (PMID 24391492, 2014). "Co-culture with iNKT cells led to a slight increase in CD1d expression during H37Rv infection (1.9±0.1 fold change) (mean ± SEM, n = 22 experiments, p<0.0001)." (PMID 24391492, 2014). "To more directly assess the impact of NKT cell deficiency on IL-5 production by ILC2 during infection, we examined ILC2 IL-5 production in total lung cell suspensions from WT and CD1d-/- mice at 7 and 12 d.p.i. using our ex vivo ICS assay." (PMID 24068930, 2013). "CD1d mRNA levels were found to be increased upon infection of DCs with herpes simplex virus type 1 (HSV-1) or human cytomegalovirus (HCMV)." (PMID 23202469, 2012). "To test the role of CD1d in this model, we simulated infection by injecting CD1d−/− mice and controls with LPS and measured changes in metabolic gene expression." (PMID 21980475, 2011). "CD1d expression was upregulated from 2–8 weeks and then downregulated at 12 and 16 weeks post-infection." (PMID 22645653, 2011). "Infection can lead to CD1d-dependent iNKT cell activation if there is cognate recognition of microbial antigens, or if the pathogen induces sufficient cytokine production to drive the activation of self-reactive iNKT cells." (PMID 19079582, 2008). "Nevertheless, a distinct difference in viral titers from eye swabs was detected at 2 days post infection among different infection groups, in the same hCD1d-KI mice infected by wild-type versus UL56-deficient viruses and in hCD1d-KI versus CD1d−/− mice infected by the same UL56-deficient viruses." (PMID 40047437, 2025). "Ceramides are abundant, highly regulated, and efficiently captured by CD1d based on several lines of evidence, including high ceramide accumulation in CD1d-expressing gastrointestinal tissues during infection, high capture of endogenous ceramides by CD1d in cells and our TCR trap data." (PMID 39141352, 2024). "Additionally, we did not observe differences in parasite proliferation between WT and CD1d−/− infections." (PMID 39445806, 2024). "Importantly, in addition to an overall higher burden of infection, CD1d-KO mice also had increased numbers of skin-derived infected cells in the dLNs compared with WT mice." (PMID 39088280, 2024). "We also quantified tissue-resident or newly recruited CD8+ T cells in the FP skin at day 3 after infection to determine whether the reduction in CTL numbers in CD1d-KO skin was due to impaired recruitment and/or in situ proliferation of CD8+ T cells." (PMID 39088280, 2024).
infection (continued). "Indeed, delayed DENV2 clearance in the skin of CD1d-KO mice was associated with a reduced CTL response, as there were fewer total and activated CD8+ T cells in the skin of CD1d-KO mice at days 3 and 5 after infection." (PMID 39088280, 2024). "Interestingly, the CD1d tail is critical for CD1d downregulation at least in response to several infections such as HIV or Chlamydia trachomatis." (PMID 38579449, 2024). "Notably, the infection of monocytes by the human pathogen M. tuberculosis results in reduced CD1d mRNA expression, indicating the transcriptional control of Cd1d expression by a mycobacterial product." (PMID 37168859, 2023). "To examine whether SARS-CoV-2 downregulates CD1d in our mouse models, we prepared single cells from mouse lungs three days post infection and stained for mouse CD1d expression." (PMID 36961850, 2023). "To investigate whether SARS-CoV-2 E protein is responsible for the CD1d downregulation in mouse infection, we transiently transfected 293T cells with plasmids expressing mouse CD1d in the presence or absence of E protein expression." (PMID 36961850, 2023). "Investigating the role of CD1d-restricted NKT cells in terms of mortality percentage and infection-associated histological markers, on the Balb/c background NKT cells seem protective, while on the C57BL6 background were not, since CD1d−/− C57BL6 mice experienced partial protection against disease." (PMID 37964320, 2023). "Since then, there have been more than a dozen α-GalCer analogues being described to date, all of which are able to stimulate iNKT cells in the context of CD1d molecules, resulting in exerting activities against various infections, cancers and auto-immune diseases primarily in a mouse model." (PMID 37402814, 2023). "Therefore, we established another in vitro SARS-CoV-2 infection assay to study the elimination of virus-infection promoted inflammatory monocytes by AlloHSC-iNKT cells via iNKT TCR/CD1d recognition." (PMID 35313965, 2022). "The antibodies may be part of a specific adaptive response: other borrelial lipid antigens are presented to T cells by CD1d after phagocytosis, and a humoral response to lipid antigens has been demonstrated after infection by other pathogens." (PMID 35289310, 2022). "Furthermore, the CD1d-labeled area in the spleens of WT mice was significantly smaller at 24 h post-infection as compared with that in uninfected mice." (PMID 34040603, 2021). "Alternatively, the infection of APCs or different pathologic conditions increase or decrease the expression of CD1d molecules on their surfaces and subsequently, the amount and frequency of self-antigens presented to NKT cells resulting in altered NKT cell activation." (PMID 34595131, 2021). "Similarly, LCVM infection also causes a reduction in CD1d expression, whereas vaccinia virus and VSV alter the intracellular trafficking of CD1d molecules, and HSV-1 alters CD1d recycling." (PMID 34073578, 2021). "The results from CD1d and Ly6G staining show that neutrophil clusters were in close contact with MZ B cells at 3 h after systemic S. aureus infection, whereas neutrophils were scattered around the outer ring of MZ B cells at 24 h post-infection." (PMID 34040603, 2021). "Once identified, this lipid could be loaded onto a CD1d tetramer to track type II NKT cells in vivo during infection." (PMID 33312179, 2020). "In conclusion, CD1d-restricted NKT cells seem to be detrimental during the disease caused by hRSV in mice as CD1d-deficientmice are less susceptible to hRSV, but not during an hMPV infection." (PMID 32463330, 2020). "Invariant natural killer T (iNKT) cells produce copious amounts of cytokines in response to T-cell receptor (TCR) stimulation by recognizing antigens such as α-galactosylceramide (α-GalCer) presented on CD1d; thus, orchestrating other immune cells to fight against pathogen infection and tumors." (PMID 30245690, 2018).